CTLA4 (cytotoxic T-lymphocyte associated protein 4)
Diseases named in the same sentence as CTLA4 in open-access papers (continued):
Sharing a sentence is not in itself a finding about the gene and the disease.
melanoma (continued). "As a first application, we compared the OS and PFS of melanoma patients treated at CHUV with CTLA4, PD1, and the combination CTLA4+PD1, with the published results of the pivotal RCT Checkmate 067 (CM-067) that led to the approval of these treatments (Ipilimumab for CTLA4 and Nivolumab for PD1)." (PMID 37025593, 2023). "It has been shown in a mouse model of melanoma that treatment with anti-CTLA-4 antibody or interleukin 2 (IL-2) immunotherapy leads to persistent production of intratumoral tumor necrosis factor alpha (TNF-α) and T cell accumulation, which increases EZH2 expression." (PMID 37325482, 2023). "However, ipilimumab is the first and only CTLA-4 inhibitor approved by the FDA in 2011 for the treatment of melanoma (a type of skin cancer)." (PMID 37106400, 2023). "Current therapeutic options in advanced melanoma include PD-1 inhibitors associated or not with CTLA-4 or lymphocyte-activating gene (LAG)-3 inhibitors and in cases of BRAF V600E/K mutated BRAF inhibitors, called targeted therapy." (PMID 37569757, 2023). "Therefore, we categorized 170 melanoma patients as high and low expressers of CTLA4 based on the optimized cut-point for survival analysis." (PMID 37197667, 2023). "Our study reveals that the post-transcriptional silencing of CTLA4 by miRNA-155 in Treg cells may contribute to reducing CTLA4 mRNA expression observed in melanoma patients." (PMID 37197667, 2023). "Additionally, it was discovered that radiotherapy paired with dual immune checkpoint blockers had a better outcome for patients with malignant melanoma than radiotherapy combined with CTLA-4 blockers." (PMID 36677919, 2023). "The anti-CTLA-4 antibody ipilimumab was the first immune checkpoint inhibitor approved in 2011 by the U.S. Food and Drug Administration for the treatment of late-stage melanoma, paving the way for the further research of immune checkpoint blockade." (PMID 37427115, 2023). "In the field of tumor immunotherapy, researchers have designed some ASOs that silenced immune suppresser gene expression, such as cytotoxic T-lymphocyte associated protein 4 (CTLA-4) and forkhead box P3 (Foxp3), and delayed tumor growth in murine melanoma models." (PMID 37175900, 2023). "The results showed that SNAI2 was a powerful prognostic biomarker in urological tumors and can effectively predict the response to anti-PD-L1 immunotherapy, and consistent results were discovered in melanoma patients treated with anti-PD-1 and anti-CTLA4 therapy." (PMID 37251370, 2023). "In addition, immune checkpoint inhibitors such as anti-PD-1 and anti-CTLA-4 have shown success in treating melanoma and non-small cell lung cancer in recent years." (PMID 37237548, 2023). "Apart from the combination with anti-PD-1, a clinical retrospective study of 101 advanced melanoma patients treated with ipilimumab (anti-CTLA-4) showed that the response rate and OS were significantly higher in the 70 patients who received RT during treatment." (PMID 37833255, 2023). "These statistical analyses demonstrate that low blood CTLA4 levels are associated with worse melanoma patient prognosis irrespective of age and sex in this cohort." (PMID 37197667, 2023). "Regarding mono-immunotherapy, either anti-CTLA-4 or anti-PD-1, several studies have shown similar efficacy and tolerability outcomes in older and younger populations, regardless of tumor type as well as in series focusing on melanoma." (PMID 37686606, 2023). "Nathanson cohort contained 21 melanoma patients who received anti‐CTLA‐4 monotherapy." (PMID 36151761, 2023). "Following the first clinically used ICI, the CTLA-4 inhibitor ipilimumab, has been approved for the treatment of advanced melanoma, PD-1 inhibitors and PD-L1 inhibitors have also been shown to significantly prolong survival of melanoma." (PMID 38186580, 2023).
melanoma (continued). "This multi‐center real‐world data study including 336 Asian patients with advanced BRAF V600‐mutant melanoma showed that the superiority of Anti‐PD‐1/CTLA‐4 over BRAF/MEK inhibitor appears modest, and the BRAF/MEK inhibitor remains a feasible first‐line treatment option." (PMID 37584204, 2023). "Similarly to the other melanoma subtypes, the combination of anti-PD-1 and anti-CTLA-4 seems to improve patients’ outcomes over monotherapy." (PMID 36674809, 2023). "In addition to melanoma, dual blockade of CTLA-4 and PD-1 was studied in a murine breast cancer model." (PMID 37928556, 2023). "For its part, intrinsic CTLA-4 expression in melanoma cells would also be IFN-γ-dependent." (PMID 36901916, 2023). "Another study aimed to explore the synergistic effect of genetically engineered NDV LaSota L289A expressing anti-CTLA4 along with radiotherapy (10 Gy) as well as the systemic administration of anti-CTLA4 +NDV L289A+ radiotherapy (10 Gy) in a B16-F10 melanoma mouse model." (PMID 37629483, 2023). "Indeed, we found that pseudoprogression was more frequent in malignant melanoma and mainly in those patients treated with anti-CTLA4 agents." (PMID 36765835, 2023). "Then, we calculated the numTS values for the selected miRNAs using the RNA-Seq data of 105 advanced melanoma samples collected from patients before and after nivolumab (anti-PD-1 agent) and ipilimumab (anti-CTLA-4) administration (pre- and post-treatment, respectively)." (PMID 38188295, 2023). "TERT promoter mutations and TERT expression are proposed as prognostic biomarkers in melanoma and TERT promoter mutations might be predictive under anti-CTLA4 therapy." (PMID 37418389, 2023). "It has been reported that SB-3CT, an MMP2/9 inhibitor, could improve the efficacy of anti-PD-1 and anti-CTLA-4 treatment in mouse models with melanoma and lung cancer via regulating PD-L1 expression." (PMID 36823234, 2023). "In 2011, Ipilimumab, a CTLA-4 inhibitor, was approved for melanoma." (PMID 36900015, 2023). "For instance, collective use of ipilimumab (targeting PD-1, an immune checkpoint receptor) and nivolumab (targeting CTLA-4, a co-stimulatory receptor) can strengthen the anti-tumor response in the treatment of melanoma, advanced renal cell carcinoma, and esophageal carcinoma." (PMID 37194085, 2023). "However, it is important to understand anti-CTLA-4’s mechanistic contribution to combination anti-PD-1/CTLA-4 therapy and investigate anti-CTLA-4 therapy for BRAF-wild type melanoma cases reresected after previous adjuvant anti-PD-1 therapy." (PMID 36980641, 2023). "The CheckMate‐037 trial, which evaluated nivolumab versus chemotherapy in patients with advanced melanoma who progressed after anti‐CTLA‐4 treatment, noted statistically better ORR in BRAF‐wildtype group with nivolumab, but no statistical difference in the BRAFV600 mutant patients." (PMID 37403699, 2023). "Consistent with this hypothesis, NK-like ILC1s transdifferentiating from NK cells in murine melanoma showed increased levels of CTLA-4." (PMID 36765891, 2023). "Baseline serum samples of 45 patients with melanoma treated with dual ICI (anti-CTLA-4 plus anti-PD-1 antibodies) and 44 patients with melanoma treated with anti-PD-1 monotherapy were independently collected across four different dermatology departments (Tübingen, Mannheim and Essen in Germany; St." (PMID 37525015, 2023). "Moreover, in melanoma tumors of the Gide2019 cohort, clinical advantages and therapeutic responses to PD-L1 and anti-CTLA4 blocking therapy were greater in patients with low SNAI2 expression." (PMID 37251370, 2023). "This prospective, non-interventional study was conducted in order to achieve an integrated assessment of the connection between a specific intestinal microbiota profile and antitumor immune response to immune checkpoint inhibitor therapy (anti-PD-1 and/or anti-CTLA-4) in melanoma patients." (PMID 38017389, 2023).
melanoma (continued). "To test this hypothesis, we analyzed the effects of human melanoma cell secretomes on CTLA4 expression in human PBMCs by culturing them with MCM obtained from various human melanoma cell lines." (PMID 37197667, 2023). "Currently approved c checkpoint inhibitors for the treatment of melanoma include an anti-CTLA-4 antibody ipilimumab, an anti-PD-1 antibodies nivolumab and pembrolizumab, correspondingly, their related research has also proved to be one of the hot topics in our result." (PMID 37427124, 2023). "The first U.S. Food and Drug Administration (FDA) approval of a CTLA‐4 antibody (ipilimumab) in 2011 was followed by the approval of two PD‐1 antibodies (pembrolizumab and nivolumab) in 2014, all exclusively for treatment of advanced-stage melanoma." (PMID 37420037, 2023). "Prior studies have reported an association between greater eosinophil levels and improved survival outcomes in anti-CTLA-4-treated melanoma patients compared to those receiving chemotherapy, suggesting a potential role for baseline eosinophil count as a predictive biomarker." (PMID 37903733, 2023). "Interestingly, The FDA approved relatlimab and nivolumab in patients with previously untreated advanced melanoma in March 2002 which is the second combination approved in this setting after nivolumab plus ipilimumab, an anti-CTLA-4 monoclonal antibody." (PMID 37509517, 2023). "Similarly, a higher mutational burden and neoantigen load were associated with enhanced clinical responses and survival after anti-CTLA-4 therapy in patients with melanoma." (PMID 37614504, 2023). "Interestingly, collating data from seven different cohorts of melanoma patients treated with ICBT revealed that patients treated firstly with anti-CTLA4 followed by anti-PD-1 who displayed high IFN-γ signalling in tumour biopsies responded best to ICBT." (PMID 37503572, 2023). "Moreover, transcriptomic and methylation levels of CTLA4 can be used for the same purpose in melanoma patients, thereby providing critical references for selection of cancer patients likely to respond to ICIs." (PMID 35720112, 2022). "Reduced infiltration of PD1+ and CTLA4+ T cells was observed in mice with liver metastasized melanoma compared to mice with only subcutaneous melanoma, suggesting that liver metastasis may also regulate systemic immune responses." (PMID 36761417, 2022). "They found that younger age, lack of extracranial metastases, better Karnofsky performance status score, fewer melanoma brain metastases, as well as treatment with BRAF inhibitors, anti-PD1/CTLA4 therapies, or cytokine therapy were significantly associated with improved overall survival." (PMID 35311078, 2022). "As a consequence of the molecular biology experiments, we have found that inhibiting CNTFR activity exerted a reverse regulatory role in the proliferation and migration of melanoma cells, but facilitated the expression of immune checkpoints (PD-1, PD-L1, and CTLA4)." (PMID 36034849, 2022). "Furthermore, high MIF expression levels are strongly correlated with poor clinical prognosis in advanced melanoma and was involved in poor responses to anti-CTLA-4 therapy." (PMID 35309911, 2022). "T-VEC also positively augments anti-CTLA-4 therapies in melanoma, as do other OVTs." (PMID 35515106, 2022). "Furthermore, targeting PD-1 and CTLA-4 in the clinic has shown efficacy in cancer patients, with these now being the standard of care in melanoma." (PMID 35774790, 2022). "The correlation between high TMB and the response to immunotherapy with the use of anti-CTLA-4 antibodies was significant among advanced melanoma patients, whereas the correlation between high TMB and the anti-PD-1 immunotherapy was significant among NSCLC, to give some examples." (PMID 35269988, 2022). "In 2011, the FDA approved anti-CTLA-4 mAb Ipilimumab for melanoma patients." (PMID 36679904, 2022). "The modern melanoma therapy directed against immune cells is targeted against PD-1 ad CTLA-4." (PMID 35334544, 2022).
melanoma (continued). "A considerable amount of melanoma patients show primary resistance to PD-1 and CTLA-4 inhibitors." (PMID 35158808, 2022). "Consequently, reducing S1P levels by silencing SPHK1 improves the efficacy of anti-CTLA-4 and anti-PD-1 immunotherapy, leading to significant tumor suppression and overall improved survival in mouse melanoma, breast, and colon tumor models." (PMID 35565311, 2022). "We assessed whether anti‐CTLA‐4 or anti‐PD‐1 mAbs alone or in combination increase the treatment efficacy of T cells in PBMC against melanoma–fibroblast bicellular spheroids." (PMID 35731974, 2022). "In this study, we analyzed several public cohorts and found that HRR mutation might be a potential predictor of clinical benefit to anti-CTLA-4 therapy in advanced melanoma." (PMID 35990677, 2022). "In a study employing an adenoviral vaccine encoding the gp33-41 epitope of the glycoprotein of lymphocytic choriomeningitis virus (LCMV) to treat gp33-expressing B16-F10 melanoma tumors, blocking CTLA-4 marginally improved tumor control as compared to gp33-adenovirus vaccination alone." (PMID 35651800, 2022). "The FDA has approved only four mAb treatments for melanoma to date: namely, ipilumimab, which targets CTLA4; nivolumab and pembrolizumab, which target PD-1; and opdualag, a combination therapy including nivolumab and relatlimab-rmbw which targets lymphocyte activation gene-3." (PMID 36140259, 2022). "Moreover, in melanoma patients treated with the CTLA4 inhibitor, LIAS expression was negatively correlated with infiltration of CTL (r = -6.05e-01, p = 1.69e-02)." (PMID 35982953, 2022). "Improvements in this area consist of FDA approval for monoclonal antibodies of programmed death-1 (PD-1), cytotoxic T-lymphocyte-associated antigen-4 (CTLA-4), and programmed death-ligand-1 (PD-L1) for the treatment of small-cell lung cancer, advanced melanoma, and metastatic bladder cancer." (PMID 36559202, 2022). "To confirm the value of these four subsets of immune cells in the prognosis of malignant melanoma treated with PD-1 blockade, we applied it to the independent validation set of 73 advanced melanoma patients treated with anti-PD-1 monotherapy (n = 41) or combined anti-PD-1 and anti-CTLA-4 (n = 32)." (PMID 36569825, 2022). "The expression of CD80, normally found on dendritic cells or macrophages, was increased in MDSCs in patients with malignant melanoma, and it was also up-regulated on MDSCs in a murine ovarian cancer model; its ligation of CTLA-4 through CD80 on Tregs is crucial for T cell suppression." (PMID 35628647, 2022). "Dual treatment with anti-CTLA-4 plus anti-PD-1 or anti-PD-L1 agents resulted in enhanced anti-tumor activity at the expense of increased toxicity for patients with some tumor types such as melanoma, but was unsuccessful in PDAC patients." (PMID 36077755, 2022). "To confirm the predictive value of CTC1-STN1, we curated three datasets of expression data for melanoma patients treated with anti-PD-1, anti-PD-L1, or anti-CTLA4 and one dataset of expression data for metastatic urothelial cancer patients treated with anti-PD-L1." (PMID 35368664, 2022). "Furthermore, monoclonal anti-CTLA4 antibodies such as ipilimumab have been used for the treatment of advanced forms of various cancers like melanoma." (PMID 36185403, 2022). "Although anti-CTLA-4 therapy has brought benefits in clinical trials of melanoma, refractory mCRC, hepatocellular carcinoma, and malignant mesothelioma, no improvement was observed in terms of overall survival (OS) in patients with metastatic castration-resistant prostate cancer." (PMID 36159809, 2022). "Interestingly, decreasing SPHK1 expression improves the efficacy of immune checkpoint inhibitors (anti-CTLA-4 and anti-PD-1 therapy) in melanoma, breast, and colon cancer mouse models." (PMID 35565311, 2022).
melanoma (continued). "The first randomized trial prospective randomized clinical trial assessing the tolerance and clinical benefit of fecal transplantation in patients with melanoma treated with CTLA-4 and PD1 inhibitors (PICASSO) has begun at Hôpitaux de Paris utilizing MaaT013 in combination with PD1 and CTLA-4." (PMID 35474500, 2022). "Moreover, for melanoma patients treated with CTLA-4 blockade, we found that TRIMs scores of patients response or not response to drug treatment were significantly different (p = 0.0071)." (PMID 36461099, 2022). "Subgroups with the following factors showed significantly longer OS when being treated concurrently: RT dose <60 Gy (p = 0.014), PTV > 3 cm3 (p = 0.007), other cancer types than melanoma (p = 0.006), anti-CTLA4-naïve patients (p < 0.001), low NLR (p = 0.039), steroid intake ≤4 mg (p = 0.042)." (PMID 35267546, 2022). "Additionally, STING pathway activation was necessary to the synergy between 50 μCi 90Y-NM600 and anti-CTLA4 in B16 melanoma, highlighting the essential role of this pathway in certain combination TRT and immunotherapy regimens." (PMID 36678756, 2022). "Moreover, in a preclinical mouse model of melanoma, low-dose 5-aza combined with an anti-CTLA-4 antibody has been proved to be more effective in controlling tumor growth than monotherapy." (PMID 35693795, 2022). "In a study of patients with advanced melanoma receiving immunotherapy (anti-CTLA4, anti-PD1, or combination therapy), they reported a significant decrease in circulating B cells in the combination therapy cohort, but not in patients receiving anti-CTLA4 or anti-PD1 therapy." (PMID 35300339, 2022). "HRR may serve as an independent predictor of anti-CTLA-4 therapy efficacy in patients with advanced melanoma, and their clinical value deserves further investigation." (PMID 35990677, 2022). "Previous study analyzed 1861 advanced melanoma patients and showed that anti-CTLA4 antibody (ipilimumab) could greatly prolong patients' long-term survival." (PMID 35242245, 2022). "In contrast, one study of melanoma patients who developed hypophysitis while on treatment with ipilimumab (anti-CTLA-4) showed that those who received lower dose corticosteroids had substantially better survival compared to those treated with high-dose corticosteroids." (PMID 35919497, 2022). "Gut microbes, such as Bacteroides, could also be a biomarker for predicting ICI therapeutic toxicity in advanced melanoma patients treated with combined CTLA-4 and PD-1 blockade." (PMID 35488243, 2022). "High expression of PD-L1 on melanoma cells allowed tumors to escape the anti-CTLA-4-based therapy." (PMID 35371055, 2022). "The expression of immune-related genes also correlates with prognosis and response to melanoma immunotherapy as demonstrated after analysis of 45 patients submitted to anti-CTLA-4 therapy that had tumors with increased expression of genes related to immune signature." (PMID 35495634, 2022). "Furthermore, tumor-specific ICOShi+CD4+IFNγ+ T-cells have been identified as a potential biomarker for anti-CTLA-4 response and prognosis in melanoma and bladder cancer patients." (PMID 35326731, 2022). "Since CHI3L1 null mutation or a-CHI3L1 neutralizing antibody treatment reduced metastatic spread, they do not determine if the inhibition of ICOS and ICOSL and or the induction of CTLA-4 are due to the direct effects of CHI3L1 or due to the decreased metastatic spread of melanoma." (PMID 36618349, 2022). "CD73 antibody combined with CTLA-4 mAb significantly inhibited melanoma growth." (PMID 36159861, 2022). "Also, an ongoing phase II clinical trial is investigating the biodistribution and tumor uptake of [89Zr]Zr-ipilimumab (anti-CTLA-4) in advanced melanoma (NCT03313323)." (PMID 35836956, 2022).